COL2A1 (collagen type II alpha 1 chain)
Diseases named in the same sentence as COL2A1 in open-access papers (continued):
Sharing a sentence is not in itself a finding about the gene and the disease.
myopia (32 papers, 2007 to 2026). "Predictors included family history of SS, presence of a COL2A1 pathogenic variant, and degree of myopia." (PMID 41768284, 2026). "A recent study on 13 members of a four-generation Chinese family with early-onset high myopia utilized whole-exome sequencing (WES) to identify an intronic COL2A1 variant accounting for the family’s high myopia." (PMID 41153400, 2025). "Spondyloepiphyseal dysplasia congenita (SEDC), also caused by heterozygous pathogenic COL2A1 variants, demonstrates similar ocular features including high myopia, vitreous changes, and risk of RD." (PMID 41153400, 2025). "The most common pathogenic genes responsible for high myopia with RRD were COL2A1 (10.0%, 4/40) and COL11A1 (5.0%, 2/40) and VCAN (5.0%, 2/40)." (PMID 40270540, 2025). "Huang found that 76% had high myopia (>−6D), and 69% had retinal detachment, many of which had a COL2A1 mutation." (PMID 34501218, 2021). "One study found in COL2A1 mutations that 89% had myopia, 42% had vitreous abnormalities, and 55% had at least one retinal detachment." (PMID 34501218, 2021). "In patients with COL2A1 mutations, myopia is the most common sign, which is present in 90% of patients, followed by vitreous changes, detected in 40% of patients, and cataracts, in 30% of patients." (PMID 32756486, 2020). "The mutation features of probands with high myopia or retinal detachment showed that the probands had a high prevalence of COL2A1 mutations, truncational mutations, and de novo mutations." (PMID 32756486, 2020). "Thirty-two (32/42, 76%) probands had high myopia in total, 21 (21/27, 78%) of whom had COL2A1 mutations, and 5 (5/8, 63%) had COL11A1 mutations." (PMID 32756486, 2020). "For patients with high myopia, a regular follow-up for multisystem is essential if a heterozygous variant in COL2A1 is identified." (PMID 32039712, 2020). "A case control study of mixed ethnicities showed an association between myopia and 2 SNPs in the collagen 2 alpha 1 gene (COL2A1), which maps to chromosome 12q13.11 and has been associated with familial Stickler syndrome type 1." (PMID 30111362, 2018). "The phenotypic subset associated with myopia (n = 130) was found to represent a set of 119 unique genes since 7 genes (COL2A1, COL11A1, FBN1, LTBP2, POMT1, POMT2, POMGNT1) had two or more associated phenotypes, leading to 11 duplicates." (PMID 29346494, 2018). "Of these genes only COL2A1 has been assessed for associations with common myopia with a positive result being reported." (PMID 23077567, 2012). "This argument was strengthened by the positive association between common polymorphisms of the COL2A1 gene, the causative gene underlying STL1, and myopia." (PMID 21527992, 2011). "On chromosome 12, strong evidence of association between myopia and the common allele of the COL2A1 SNP rs1635529 was found (p=0.00007, with 44 informative families) along with weak evidence for linkage (parametric LOD of 1.11)." (PMID 17653045, 2007). "The most significant association for myopia seen in the current study was for COL2A1 with a p-value of 0.00007." (PMID 17653045, 2007). "Pathogenic variants in COL2A1 are frequently associated with high myopia." (PMID 41153400, 2025). "In addition, a large study of over 250 families with high myopia found a significant association with COL2A1 single-nucleotide polymorphisms (SNPs)." (PMID 41153400, 2025). "Indeed, common polymorphisms in COL2A1 – the causative gene for STL1 – have been found to be associated with myopia in two family-based association studies." (PMID 21527992, 2011). "Therefore, we predict that mutations in the ARID1B gene would result in decreased expression of wild-type protein, relatively enhanced activity of ARIDIA protein, low expression of FGFR3 protein, and low expression of COL2A1 protein leading to clinical phenotypes associated with myopia." (PMID 38790056, 2024).
myopia (continued). "In addition, one patient with a mildly advanced bone age was found to harbor a frameshift mutation of the ACAN gene; whereas, one patient with early-onset myopia, cleft palate, flat nose, and short fingers was found to have a hemizygous mutation of the COL2A1 gene." (PMID 30541462, 2018). "The variable expressivity, even within the same family, contrasts with the high disease penetrance: In most reported COL2A1 exon 2 mutations, ocular features were variable as either myopia, retinal detachment, or retinal degeneration could be absent in affected patients." (PMID 23592912, 2013). "Mutations in COL2A1 and COL11A1 are associated with early-onset high myopia; however, myopia of ≥−10D was more common in COL2A1 than in COL11A1 (40% vs. 19%)." (PMID 34501218, 2021). "Extracellular matrix components such as collagen type I alpha 1 (COL1A1), collagen type II alpha 1 (COL2A1), lumican (LUM), decorin (DCN) and epiphycan (EPYC or DSPG3) have been previously assessed for genetic associations with myopia." (PMID 23077567, 2012). "SNPs were also analyzed in genes where their expression pattern or their association with syndromes conveys myopia as part of the phenotype (FGF2, BDNF, COL2A1, COL18A1, and PAX6)." (PMID 17653045, 2007). "Similarly to COL2A1, biallelic pathogenic variants in COL18A1 are consistently associated with high myopia as shown across cohort and case studies." (PMID 41153400, 2025). "Here, we report four patients carrying variants in the propeptide regions of COL2A1 and presenting with tall stature, arachnodactyly, dural ectasia, and varying skeletal manifestations, resembling MASS (mitral valve, myopia, aorta, skeletal and skin features) phenotype." (PMID 35296718, 2022). "Mutations causing premature stop codons in exon 2 of COL2A1 lead to ocular-only phenotypes including retinal detachment and high myopia, but with few or no other systemic manifestations." (PMID 27484908, 2016). "Hence, to date, PAX6, HGF, and UMODL1 remain the strongest candidates for high grade myopia and collagen, type 2, alpha 1 (COL2A1) for common myopia." (PMID 19365569, 2009). "Our cohort largely concurred with these findings and highlights vitreoretinopathies (e.g., COL2A1, FBN1) as significant contributors to syndromic myopia parallel to photoreceptor and synaptic dystrophies." (PMID 41465105, 2025). "These eyes had a mean refractive error of −4.50 ± 4.49D (range −0.25–−11.13D) and three of these patients (25%; ABCA4, COL2A1, KCNV2) had high myopia." (PMID 41465105, 2025). "It was found that high myopic associated proteins (ASXL1 FGFR3 ERBB3 SOX4) can affect ARID1B protein by affecting ARIDIA protein, and COL2A1 protein can also affect ARIDIA protein by affecting FGFR3 protein, resulting in the clinical phenotype of patients with high myopia." (PMID 38790056, 2024). "Families primarily presenting with high myopia have not shown linkage with the Stickler COL2A1 locus in several other studies." (PMID 17653045, 2007). "Therefore, we propose that SOX11 may directly or indirectly affect proteins with strong links to high myopia, such as COL9A1, COL2A1, and COL11A1, by affecting the expression or function of SOX4, ultimately causing the clinical phenotype of eoHM and dystrophy of cone-rod cells in CSS9 individuals." (PMID 40933692, 2025).
chondrosarcoma (25 papers, 2012 to 2025). A malignant cartilaginous matrix-producing mesenchymal neoplasm arising from the bone and soft tissue. "The second most common mutations in chondrosarcomas (ChSs) are found in the COL2A1 gene, which encodes the alpha-1 chain of type II collagen fibers in cartilage." (PMID 39590345, 2024). "The COL2A1 gene, which is responsible for encoding the alpha-1 chain of type II collagen, plays a pivotal role in developing chondrosarcomas (ChSs)." (PMID 39590345, 2024). "COL2A1 is frequently mutated in chondrosarcoma, that the mutations were accumulated across the gene footprint of COL2A1, supporting the notion of a transcription-associated mutation." (PMID 29044189, 2017). "In addition, we also selected two different mutations in the COL2A1 gene previously found in chondrosarcoma." (PMID 30987403, 2019). "Mutations in the COL2A1 gene itself have been identified in approximately one third of chondrosarcomas, which may also impair the maturation of type II collagen." (PMID 26161668, 2015). "However, mutations in COL2A1 have recently been associated with chondrosarcoma risk." (PMID 33708626, 2021). "Therefore, the down-regulation of COL2A1 in our chondrosarcoma samples might be a result of gene mutation that is independent of a decrease in the upstream regulator, SOX9." (PMID 29044189, 2017). "Mutations of the major cartilage collagen gene COL2A1, with deletions, insertions, and rearrangements, were identified in 37% of chondrosarcomas." (PMID 35163019, 2022). "Herein, we determined the effects of FYD on the expression of transcription factor SOX9 and its target gene collagen type II, alpha 1 (COL2A1) as well as the activation of Smad2/3 in interleukin- (IL-) 1β-stimulated SW1353 chondrosarcoma cells." (PMID 26770254, 2015). "Therefore, we observed a higher gene expression of SOX9, COL2A1, and COMP, the genes associated with chondrocyte maturation, in MSCs and chondrosarcoma cells treated with vitamin B6." (PMID 31683926, 2019). "COL2A1 gene also undergoes somatic alterations in chondrosarcoma and enchondroma cases." (PMID 30517191, 2018). "SOX9 might be used as a marker to distinguish grade 1 chondrosarcoma from enchondroma, while COL2A1 may be able to discriminate between grade 1 and 2 chondrosarcomas." (PMID 29044189, 2017). "We found that expression of the chondrogenic master regulator gene, SOX9, was strong in enchondromas and significantly diminished in grade 1 chondrosarcomas, while expression of the cartilage-specific collagen gene, COL2A1, was dramatically decreased in grade 2 chondrosarcomas." (PMID 29044189, 2017). "In addition, the chondrogenic master regulator, SOX9, showed differential expression between enchondroma and grade 1 chondrosarcoma, while expression of the cartilage-specific gene, COL2A1, was decreased in grade 2 chondrosarcoma compared with grade 1." (PMID 29044189, 2017).
chondrosarcoma (continued). "Recent studies have suggested several promising biomarkers and therapeutic targets for chondrosarcoma, including isocitrate dehydrogenase (IDH1/2) and COL2A1." (PMID 38541003, 2024). "Recent studies have suggested several promising biomarkers and therapeutic targets for chondrosarcoma, including IDH1/2 and COL2A1." (PMID 35163019, 2022). "Recent studies have suggested several promising biomarkers and therapeutic targets for chondrosarcoma, including IDH1/2, COL2A1, and PD-L1." (PMID 35163019, 2022). "To determine if the increased COL2A1 expression upon TGF-β2 knockdown under physosmotic conditions (i.e., in PM) was accompanied by an increased reporter assay activity, we repeated the experiment in the established chondrosarcoma cell line SW1353." (PMID 30781744, 2019). "The cartilage-specific collagen gene, COL2A1, was also appreciably expressed in enchondromas, and its expression tended to decrease in grade 1 chondrosarcoma, but not significantly, whereas it was dramatically attenuated in grade 2 chondrosarcomas." (PMID 29044189, 2017). "To investigate if any of these CNSs could enhance Col2a1 expression, we made luciferase reporter constructs and examined their enhancer activity in HTB-94 human chondrosarcoma cell line." (PMID 22815835, 2012).
Stickler syndrome type 1 (25 papers, 2012 to 2025). "Our findings expand the known mutational spectrum of COL2A1 and further illustrate the phenotypic variability of an ocular variant of Stickler syndrome type I with minimal systemic manifestations." (PMID 41050055, 2025). "Heterozygous pathogenic mutations in COL2A1 are associated with type I Stickler syndrome which results from the improper formation of collagen." (PMID 41153400, 2025). "Our findings expand the mutational spectrum of COL2A1 and enhance the understanding of the phenotypic variability associated with an ocular variant of Stickler syndrome type I with minimal systemic manifestations." (PMID 41050055, 2025). "This study aims to explore the correlation between a novel COL2A1 mutation and an ocular variant of Stickler syndrome type I with minimal systemic manifestations." (PMID 41050055, 2025). "The fetus with Stickler syndrome type I (OMIM# 108300) caused by a heterozygous COL2A1 missense mutation (case 10) displayed rhizomelic shortening and bowing of the long bones as well as microretrognathia and clenched hands on ultrasound." (PMID 36900003, 2023). "In stark contrast, congenital eye anomalies are observed together with facial defects in Stickler syndrome Type I, reflecting an autosomal dominant mutation in COL2A1." (PMID 36278547, 2022). "The predominance of these fibers in cartilage is consistent with the early onset osteoarthritis found in many COL2A1-deficient individuals with type I Stickler syndrome." (PMID 36278547, 2022). "The common Stickler syndrome type I is inherited as an autosomal dominant trait, with causal mutations in collagen type II alpha 1 (COL2A1)." (PMID 23592912, 2013). "Type I Stickler syndrome (STL1) is associated with mutations in the COL2A1 gene encoding type II collagen, while mutations in COL11A1 and COL11A2 encoding type XI collagen, are associated with type II (STL2) and type III Stickler syndrome (STL3) respectively." (PMID 23110709, 2012). "In Stickler syndrome Type I, these defects are ascribed to autosomal dominant mutations in the COL2A1 gene and can result in significant visual impairment or, in some cases, may lead to blindness." (PMID 36278547, 2022). "Stickler syndrome type I (ocular form) is caused by mutation in the COL2A1 gene." (PMID 28018693, 2016). "The most prevalent form, Stickler syndrome type I (STL1, MIM #108300), is predominantly caused by defects in the COL2A1 gene." (PMID 39050257, 2024). "Further, infantile-onset glaucoma is also reported in Type I Stickler syndrome indicating a greater role for COL2A1 in eye development." (PMID 36278547, 2022). "The COL2A1 gene (OMIM:120140), located on chromosome 12q13.11, is the causative gene for Stickler syndrome type I. It encodes the α1 chain of type II collagen, a structural protein composed of three α1(II) chains that is highly expressed in the vitreous body of the eye." (PMID 41050055, 2025). "Premature stop codons in COL2A1 exon 2 lead to a Stickler syndrome type I ocular-only phenotype with few or no systemic manifestations." (PMID 23592912, 2013).
type II collagenopathies (25 papers, 2011 to 2025). "Czech dysplasia is distinguishable from other type II collagenopathies by a single missense mutation in the COL2A1 gene (R275C, c.823C > T)." (PMID 39902299, 2024). "Mutations in the COL2A1 gene give rise to a diverse group of disorders collectively termed type II collagenopathies." (PMID 39902299, 2024). "One exemplary type-II collagenopathy is the chondrodysplasia caused by the autosomal-dominant c.3508 GGT > AGT mutation in exon 50 of COL2A1, leading to a p.Gly1170Ser substitution in the C-terminal region of the procollagen-II triple-helical domain." (PMID 38981683, 2024). "Type-II collagenopathies are overwhelmingly caused by mutations specifically within the procollagen-II triple helix-encoding portion of the COL2A1 gene." (PMID 38981683, 2024). "Alterations in the amino acid arrangement of type II collagen due to COL2A1 variants can affect the structural stability and function of the protein helix, leading to type II collagenopathies (MIM #120140)." (PMID 39050257, 2024). "Mutations in the gene encoding collagen-II (COL2A1) often lead to diseases termed type-II collagenopathies, including many chondrodysplasias." (PMID 38981683, 2024). "Pathogenic variants in the COL2A1 gene lead to a series of diseases collectively referred to as type II collagenopathies, which are characterized by skeletal dysplasia." (PMID 39050257, 2024). "WES analysis confirmed that case 42 was heterozygous for the COL2A1 (NM_001844.4) c.2303G > T variant, resulting in a protein change: p.G768V, consistent with severe type 2 collagenopathy." (PMID 36352425, 2022). "Pathogenic sequence variants in the COL2A1 gene cause clinically distinguishable type II collagenopathies with mild to lethal phenotypes, which are usually of dominant inheritance." (PMID 35296718, 2022). "Type II collagenopathies caused by pathogenic variants in the COL2A1 gene are characterized by a wide range of clinical and radiological signs, and their modification can occur across ages." (PMID 35052477, 2022). "A novel homozygous variant of the COL2A1 gene was identified and the patient was diagnosed with type II collagenopathy." (PMID 34380476, 2021). "The common molecular bases of the type II collagenopathies are heterozygous mutations in the type II collagen gene (COL2A1), which encodes the precursor of the type II collagen α1 chain, the most abundant cartilage component." (PMID 34088323, 2021). "Type II collagenopathies are resulted by mutation of COL2A1 (MIM #120140) and are inherited in an autosomal dominant manner." (PMID 34380476, 2021). "Molecular defects of the COL2A1 gene cause type II collagenopathies that is mainly an autosomal dominant disease, whereas some rare cases with autosomal recessive inheritance of mode have also been identified." (PMID 34380476, 2021). "We identified a novel homozygous variant of the COL2A1 gene as the cause of type II collagenopathies in a Chinese male, enriching the spectrum of genotypes." (PMID 34380476, 2021). "COL2A1 mutations have been associated with various human disorders, which are collectively termed type II collagenopathies." (PMID 34088323, 2021). "Spondyloepiphyseal dysplasia congenita (SEDC, OMIM #183900) is a bone dysplasia with autosomal dominant inheritance caused by a heterozygous mutation in the COL2A1 gene (type II collagenopathy)." (PMID 28265456, 2017). "Spondyloepiphyseal dysplasia congenita (SEDC, OMIM #183900) is one of the type II collagenopathies caused by a heterozygous mutation in the COL2A1 gene." (PMID 28265456, 2017). "Mutations in the COL2A1 gene cause type II collagenopathies characterized by skeletal dysplasia with a wide spectrum of phenotypic severity." (PMID 28738883, 2017). "Of all the reported mutations in the C-propeptide region that result in short-stature type II collagenopathies, our mutation is the farthest truncating mutation from the C-terminal of COL2A1." (PMID 27955642, 2016).